PPP2CA (protein phosphatase 2 catalytic subunit alpha)
Diseases named in the same sentence as PPP2CA in open-access papers (continued):
Sharing a sentence is not in itself a finding about the gene and the disease.
tumor (42 papers, 2009 to 2025). "Triptolide significantly suppressed tumor growth in the PPP2CA-knockout group within two weeks, effectively reversing the tumor-promoting effects of PPP2CA deficiency." (PMID 40770810, 2025). "PPP2CA deficiency accelerated tumor growth, with larger tumor volumes and greater tumor mass observed in the PPP2CA-knockout group compared to controls." (PMID 40770810, 2025). "Mechanistically, YTHDF2 enhanced expression of PPP2CA, the catalytic subunit of PP2A (Protein phosphatase 2A), in an m6A-independent manner, and silencing of PPP2CA antagonized the anti-tumor effects caused by overexpression of YTHDF2 in GC cells." (PMID 36870954, 2023). "Thus, although knocking down PPP2CA (a gene with tumor-suppressive effects) increases cell susceptibility to ferroptosis, this increased susceptibility typically indicates decreased malignant phenotype of cells." (PMID 41278282, 2025). "CRISPR-Cas9 was applied to knock out PPP2CA, examining its effect on lactate production and tumor progression." (PMID 40770810, 2025). "As shown, MKRN2-OE markedly inhibited tumor burdens compared to the control vector group, while PPP2CA-OE reversed the growth inhibition upon MKRN2-OE." (PMID 40959281, 2025). "In summary, MKRN2 suppresses ccRCC progression, primarily influencing tumor cell apoptosis via PPP2CA-mediated Wnt signaling." (PMID 40959281, 2025). "By suppressing ITGA5, Triptolide reversed cancer progression and restored tumor-suppressive effects in a PPP2CA-knockout xenograft model." (PMID 40770810, 2025). "In our study, we show that ITGA5, as a downstream target of the PPP2CA, plays multiple critical roles in tumor metabolic reprogramming and metastasis." (PMID 40770810, 2025). "PPP2CA has been recognized as a tumor suppressor involved in metabolic regulation, but its role in lactate metabolism in OC had yet to be determined." (PMID 40770810, 2025). "Based on these findings, we propose that MKRN2 and PPP2CA have opposite regulatory effects on β-Catenin protein expression, leading to functional equilibration of the Wnt signaling that mediates ccRCC tumor progression." (PMID 40959281, 2025). "PPP2CA exerts tumor-suppressive effects, and its knockdown increases the sensitivity of cells to ferroptosis." (PMID 41278282, 2025). "We predicted the associated miRNAs of target hub genes, 12 for PPP2CA followed by 7 for HSP90AA1 and 4 for EFGR, which would be further analysed for their role in tumour expression or repression." (PMID 39434198, 2024). "A previous study has indicated that PPP2CA has potential to serve as a tumor suppressor gene across various cancers, with its expression potentially modulated by rs13187105 or other SNPs that exhibit strong linkage disequilibrium." (PMID 39751645, 2024). "One of the first degree interactors of Pirin is PPP2CA, which is a serine/threonine phosphatase with activities critical for maintaining healthy cellular functions and suppressing tumor." (PMID 38033031, 2023). "In a breast tumor mouse model, miR-183 in exosomes derived from tumor cells decreased tumor growth and promoted pro-inflammatory cytokines by targeting PPP2CA." (PMID 35884901, 2022). "The SET inhibitor OP449 effectively decreased the viability of NB cells, independent of their molecular alterations and in line with a tumor suppressor function of PPP2CA." (PMID 35814385, 2022). "The contrasting concentration-dependent functions of PPP2CA as an essential survival gene at low expression levels and a tumor suppressor at high levels are reminiscent of other genes showing this so-called Goldilocks phenomenon." (PMID 35814385, 2022). "Particularly ATM, PPP2CA, and HDACs are known to mediate the vulnerability of tumor cells towards irradiation and chemotherapeutic drugs." (PMID 31354846, 2019).
tumor (continued). "The PPP2CA protein, a known tumor suppressor, is a pervasive critical node, also at first order PPIN level." (PMID 28824643, 2017). "Additionally, Immunohistochemical staining for Ki-67 further confirmed increased proliferation in the PPP2CA-knockout tumors, supporting its role as a tumor suppressor in OC progression." (PMID 40770810, 2025). "Finally, patient-derived organoids, xenograft tumor model, and lactate assays assessed Triptolide’s reversal effect on PPP2CA dysregulation-driven OC progression." (PMID 40770810, 2025). "The catalytic subunit of protein phosphatase 2A (PP2A), PPP2CA, might mediate the tumor-suppressor roles of YTHDF2 in an m6A-independent manner." (PMID 36870954, 2023). "Finally, PPP2CA is a targetable tumor suppressor that can be achieved by PP2A-activating drugs or by antagonists of PP2A inhibitors." (PMID 36870954, 2023). "However, activation of PPP2CA by the SET inhibitor OP449 also led to growth inhibition of the cells, in line with a tumor suppressor function of PPP2CA." (PMID 35814385, 2022). "PPP2CA encodes for the catalytic unit of phosphatase 2A (PP2A), which acts as a tumour suppressor." (PMID 34885088, 2021). "We found the tumor suppressor PPP2CA to be upregulated by ML." (PMID 31354846, 2019). "As a tumor suppressor gene, Ppp2ca is a hotspot for tumor treatment." (PMID 27213341, 2016). "This phenomenon may be attributed to the ability of PPP2CA knockdown to regulate the biological behavior of tumor cells through multiple mechanisms, with the ultimate enhancement of the malignant phenotype resulting from the combined effects of these mechanisms." (PMID 41278282, 2025). "Herein we have unveiled a hitherto obscure role of NLRP4, which orchestrated direct interaction with PPP2CA/B, subsequently triggering chemokine reprogramming through PI3K-Akt-NF-kB axis and thus curtailing tumor growth in a T-cells-independent manner." (PMID 40087771, 2025). "Inhibited the expression of PPP2CA, which could promote the release of pro-inflammatory cytokines such as IL-1b, IL-6, and TNF-a from macrophages stimulating tumor invasion." (PMID 36612080, 2022). "PPP2CA expression was significantly decreased in GC tissue (32 tumor samples vs. 32 normal samples; P = 3.76e − 02), while METTL3 expression was increased significantly in GC tissue (415 tumor samples vs. 35 normal samples; P = 7.32e − 06)." (PMID 34485508, 2021). "In this study, we observed that the PPP2CA coding sequence is not polymorphic in various tumour cell lines tested." (PMID 24460909, 2014). "However, in patients with high PPP2CA expression, neither ITGA5 nor ITGB1 exhibited a significant association with overall survival, suggesting that PPP2CA may play a regulatory role in integrin-mediated tumor progression." (PMID 40770810, 2025). "Increased protein phosphatase A catalytic subunit alpha (PPP2CA) levels and reduced H4R3me2 were observed in HCV-positive HCC tumor samples compared to matching non-tumor liver tissue." (PMID 34361112, 2021).
cancer (33 papers, 2009 to 2026). A tumor composed of atypical neoplastic, often pleomorphic cells that invade other tissues. "PPP2CA has been reported to be associated with several types of cancer, including prostate cancer, non-small cell lung cancer and acute myeloid leukemia." (PMID 28904398, 2017). "Protein phosphatase 2 (PP2A) with its catalytic subunit PPP2CA is a major phosphatase in cancer cells, including NB." (PMID 35814385, 2022). "In silico data mining of genome-scale CRISPR/Cas9 knock-out screens confirmed the dependency of KELLY cells on PPP2CA and extended this conclusion to other NB cell lines and additional cancer entities." (PMID 35814385, 2022). "PPP2CA, which encodes the alpha isoform of the catalytic subunit of PP2A, has been recently reported to be associated with several types of cancers." (PMID 28904398, 2017). "Given its established role in cancer biology and growing evidence implicating PP2A in glycolysis control, the specific involvement of PPP2CA in glycolytic reprogramming and metabolic adaptation in OC warrants further investigation." (PMID 40770810, 2025). "These cell lines showed a spectrum of genetic dependencies on KRAS, HRAS, BRAF, CALM1-3 (the three human CaM genes), the alpha isoform of the C subunit of the PP2A enzyme (PPP2CA) and an endogenous inhibitor of PP2A in cancer, SET." (PMID 35617282, 2022). "The downexpression of these miRNAs significantly reduced cancer cell proliferation and apoptosis by targeting FOXO-3, CLSPN, ACVR1B, E2F4 and PPP2CA and regulated cell cycle progression by targeting CDKN2A and FOXO-3." (PMID 34743742, 2021).
infection (9 papers, 2012 to 2022). The state of being infected such as from the introduction of a foreign agent such as serum, vaccine, antigenic substance or organism. "Phenylephrine (20 μmol/L) significantly induced both Nppa and Nppb in NRVCs, and this induction was completely blocked by infection with adenovirus-expressing PPP2CA." (PMID 30050113, 2018). "Using qRT-PCR, we demonstrated that S. japonicum infection significantly increased expression of Prkab1, but not Ppp2ca, and Pafah1b1 in the livers of ND-fed mice compared with that in the control mice with infection." (PMID 33391522, 2021). "Ad-HDAC2 S394E successfully increased HPG incorporation despite the infection of Ad-PPP2CA (6th column), whereas Ad-HDAC2 WT failed to overcome the suppression of PPP2CA (4th column)." (PMID 30050113, 2018).
neurodevelopmental disorder (5 papers, 2022 to 2024). A behavioral and cognitive disorder with onset during the developmental period that involves impaired or aberrant development of intellectual, motor, or social functions. "This approach identified two class 1 genes: PPP2CA and PTPN4, for which multiple variants have recently been reported as being linked to neurodevelopmental disorders, validating our approach." (PMID 37056996, 2023). "Specifically, PP2A-related neurodevelopmental disorders are characterized by mutations in PPP2R1A (Aα), PPP2CA (Cα), PPP2R2C (B55γ), PPP2R5B (B56β), PPP2R5C (B56γ), and PPP2R5D (B56δ), with most patients and mutations, so far, found in PPP2R5D." (PMID 36313552, 2022). "Fifteen heterozygous, de novo variants affecting PPP2CA have thus far been identified in sixteen individuals with a neurodevelopmental disorder, of which one full gene deletion, one insertion, four nonsense variants, and nine missense variants (OMIM#618354)." (PMID 36313552, 2022).
PPP2CA also shares sentences with these, for which no sentence is quoted: asthma (4 papers); lung carcinoma (4); colorectal cancer (3); Insulin resistance (3); tauopathies (3); autism (2); bladder cancer (2); depression (2); endothelial dysfunction (2); neurodegenerative disease (2); Obesity (2); renal fibrosis (2); acute myeloid leukemia (1); Ataxia (1); atrial septal defect (1); autism spectrum disorder (1); Autoimmunity (1); bipolar disorder (1); breast adenocarcinoma (1); Chlamydia infection (1); chronic lymphocytic leukemia (1); clear cell renal cell carcinoma (1); cyst (1); diastolic heart failure (1); dyslipidemia (1); enteritis (1); Epileptic encephalopathy (1); esophageal cancer (1); esophageal squamous cell carcinoma (1); folate deficiency (1).
A further 30 diseases each share a sentence with PPP2CA in 1 paper.